INS (insulin)
Diseases named in the same sentence as INS in open-access papers (continued):
Sharing a sentence is not in itself a finding about the gene and the disease.
metabolic syndrome (continued). "Gypenosides isolated from G. pentaphyllum have been identified to improve metabolic syndrome via insulin secretion stimulation, glucose uptake promotion and gut microbiota modulation." (PMID 32943612, 2020). "An increased beta cell function coupled with poor insulin sensitivity has been reported for individuals with metabolic syndrome, this situation was evidenced at the beginning of the study while a reduction at the end was observed." (PMID 32831908, 2020). "Collectively, our studies support that lipid-lowering actions are critical for glucose-lowering effects of leptin, and demonstrate that LEPRs in RIP-Cre25Mgn neurons mediate anti-dyslipidemia actions of leptin in an insulin-independent manner." (PMID 33071988, 2020). "In a recently published phase I/II trial in humans with the metabolic syndrome, supplementation with A. soehngenii was shown to be safe and to improve insulin sensitivity after 4 weeks of daily treatment." (PMID 32880688, 2020). "In a study, Rajupadiaet reported that garlic can improve insulin sensitivity, while, metabolic syndrome and oxidative stress reduced the amount of food in rats." (PMID 32042381, 2020). "The treatment was associated with weight loss, decreased body fat mass, increased utilization of body fat toward energy, preservation of insulin sensitivity and pancreatic β cell mass, and reduction of dyslipidemia, hepatic steatosis, and liver injury." (PMID 32218769, 2020). "Acute intake of EVOO significantly ameliorates insulin sensitivity and glycemia in patients with metabolic syndrome by modulating the expression of genes involved in inflammation, metabolism, and cancer." (PMID 33374501, 2020). "The insulin level of patients with metabolic syndrome exhibited a significant (p < .05) difference among all three groups." (PMID 32566179, 2020). "C. elegans contains many key metabolic-related components such as oxidative stress and insulin signaling pathways, making it a useful platform to improve our understanding of complex diseases such as metabolic syndrome." (PMID 33101582, 2020). "In the present study, both parameters of hyperinsulinemia (glucose, insulin, HbA1c, and C-peptide) and dyslipidemia (cholesterol, triglyceride, HDL, LDL, and VLDL) were similar between AR and AP groups at the end of 12 months." (PMID 32968385, 2020). "The same study found that myostatin levels are correlated with the number of metabolic syndrome criteria met, insulin levels and insulin sensitivity." (PMID 32796600, 2020). "Improved insulin sensitivity was [+also] demonstrated after a protocol of aerobic exercise training or combined exercise training in a model of metabolic syndrome." (PMID 32521542, 2020). "PCOS women with CC genotype have higher levels of insulin and simultaneously, showed dyslipidemia (high cholesterol, TG, LDL, and low HDL)." (PMID 33033446, 2020). "Beneficial effects included decreased disease severity, improved mental health, metabolic parameters, mainly insulin sensitivity, dyslipidemia, inflammation, and antioxidative capacity, and lower use of healthcare." (PMID 33396898, 2020). "These markers can contribute to blood pressure, waist circumference, and insulin sensitivity and then form metabolic syndrome." (PMID 32549270, 2020). "Since skeletal muscle constitutes a significant tissue mass of the body, insulin resistance within the muscle is considered to initiate the onset of diet-induced metabolic syndrome." (PMID 32977552, 2020). "Metabolic syndrome is defined as having three of the following five characteristics: high blood pressure, high BMI, dyslipidemia, impaired insulin sensitivity, and a large waist circumference." (PMID 32092101, 2020). "Maternal HFD also programmed the development of metabolic syndrome, characterized by increases in fasting plasma insulin, glucose, triglyceride and leptin levels, as well as HOMA index." (PMID 32446297, 2020).
metabolic syndrome (continued). "In T1DM patients, other frequent complications were the following, in decreasing range of frequency: insulin lipodystrophies (67.3%), dawn phenomenon (42.3%), and dyslipidemias (26.9%)." (PMID 33202729, 2020). "4‐HIL has attracted a great deal of attention due to its considerable insulin secretion promotion effects, enhancement of resistance to insulin in peripheral tissues, and dyslipidemia regulation." (PMID 32625042, 2020). "A study conducted with young overweight Latino subjects revealed increased cortisol and fasting insulin levels in addition to increased 2 h glucose and insulin (during OGTT) levels among youth with metabolic syndrome." (PMID 33192210, 2020). "In patients with metabolic syndrome, fatty liver occurs because of an increased uptake of fatty acids accompanied by an impairment in insulin action in adipose tissue." (PMID 33105604, 2020). "In other words, orally encapsulated INP was more effective in correcting dyslipidemia in comparison to injectable insulin." (PMID 32695298, 2020). "ALiOS feeding resulted in metabolic syndrome, as indicated by an increase in serum insulin and leptin levels and a drop of adiponectin levels." (PMID 33202693, 2020). "The differences between responses of individual older mice (control vs. SFN diet) to insulin suggest that old mice on control diet began to develop metabolic syndrome and pathology." (PMID 33067900, 2020). "Non-clinical investigations have suggested an interdependence between insulin and the NO–sGC–cGMP signalling pathway in both the endothelium and metabolically active tissues that are disrupted in the metabolic syndrome." (PMID 31858186, 2020). "In metabolic syndrome in schizophrenia, the effect of berberine administration on insulin secretion, insulin sensitivity and metabolic syndrome was evaluated." (PMID 33198257, 2020). "In humans, FMT with feces from lean donors in subjects with metabolic syndrome led to increased insulin sensitivity." (PMID 32266160, 2020). "The inoculation of butyrate producing gut microflora in germ-free-lean mice with metabolic syndrome also showed improved insulin sensitivity." (PMID 32708684, 2020). "Insulin treatment prevented dyslipidemia, since the triglycerides and total cholesterol levels in the plasma of DINS rats were similar to those of NYOG rats." (PMID 32566072, 2020). "Recently, Saroglitazar has stimulated interest of physicians for treatment of NAFLD due to its dual effect in improving dyslipidemia and insulin sensitivity." (PMID 33273703, 2020). "Exercise can prevent metabolic syndrome and can also result in reversal of muscle insulin resistance and reduction of postprandial lipogenesis." (PMID 32808252, 2020). "Insulin, total cholesterol, LDL-C, HDL-C, and total cholesterol-to-HDL ratio are usually altered in postmenopausal women with a 50% risk of having metabolic syndrome." (PMID 31941004, 2020). "This was emphasized in a recent report where having a combination of low HDL levels and high TG accompanied by reduced insulin sensitivity defined atherogenic dyslipidemia." (PMID 32832558, 2020). "As a consequence, the elevated release of FFA affects liver functioning and insulin signaling, leading to dyslipidemia, hyperinsulinemia, glucose intolerance and IR." (PMID 32330202, 2020). "Overexpression of adiponectin in mice improves dyslipidemia, insulin sensitivity, and glucose tolerance." (PMID 33255404, 2020). "The roles of the peripheral CB1 antagonist AM6545 and the CB1 neutral antagonist AM4113 on insulin resistance development using the high-fructose/high-salt model of metabolic syndrome were investigated in the present study." (PMID 33138155, 2020).
metabolic syndrome (continued). "Global deletion of Gprc6a in mice is reported to result in a metabolic syndrome-like phenotype and conditional deletion of Gprc6a in pancreatic β-cell and skeletal muscle respectively impair insulin secretion and glucose uptake." (PMID 32350388, 2020). "Moreover, they have less ectopic fat storage and smaller adipocyte cells that serve better adipose function, resulting in higher insulin sensitivity and thus lower risk of metabolic syndrome (MetS) and type- 2 diabetes." (PMID 33372634, 2020). "High fructose intake triggers de novo lipogenesis and promotes features of the metabolic syndrome, including hepatic steatosis and inflammation or elevated levels of serum insulin and triglycerides." (PMID 32733884, 2020). "Greater adiposity, insulin insensitivity, and inflammatory responses, resembling the metabolic syndrome, were induced in the third-trimester versus first-trimester mice, suggesting there is a microbial component mediating host immunity and metabolism." (PMID 33029392, 2020). "In our rat model of metabolic syndrome, MG exposure impaired adipose tissue insulin sensitivity and potentiated inflammation at both transcriptome and metabolic levels, pointing to the possible role of MG in adipose tissue dysfunction." (PMID 32878255, 2020). "Moderate drinking is known to contribute to lowering the risk of metabolic syndrome by increasing HDL-C levels and lowering blood glucose through improving insulin-mediated glucose uptake." (PMID 32357485, 2020). "In a human study, FMT from lean donors to individuals with metabolic syndrome temporarily increases insulin sensitivity." (PMID 32825440, 2020). "Results showed that 8-week GHP supplementation significantly decreased fasting blood glucose levels, restored insulin production, improved glucose tolerance and insulin tolerance, and alleviated dyslipidemia in T2D mice." (PMID 31952248, 2020). "Transplantation of intestinal microbiota from healthy, lean donors improved insulin signaling in participants with metabolic syndrome, suggesting that modulating gut microbiota is helpful for ameliorating T2D." (PMID 31952248, 2020). "The Metabolic Syndrome in Men study demonstrated that insulin sensitivity was already decreased substantially within the normal range of fasting plasma glucose." (PMID 32587566, 2020). "Of note, T2D dyslipidemia is avoided upon knocking out the IR, implying an obligatory role for insulin in promoting T2D dyslipidemia." (PMID 32128655, 2020). "SCA is a common and growing problem in type 2 DM given the interrelatedness of abnormalities in glucose/insulin homeostasis, dyslipidemia, coronary atherosclerosis, myocardial fibrosis, and QT interval prolongation." (PMID 32098624, 2020). "Obese and metabolic syndrome patients have both insulin and leptin resistance leading to appetite stimulation further exacerbating rises in insulin and leptin levels." (PMID 32708430, 2020). "Collectively, our data demonstrate that LEPRs in RIP-Cre25Mgn neurons significantly contribute to glucose-lowering effects of leptin in an insulin-independent manner by improving dyslipidemia." (PMID 33071988, 2020). "Impaired glucose tolerance is characterized by insufficient insulin response in the peripheral target tissues, and it is a key point in the development of the metabolic syndrome." (PMID 33348926, 2020). "At 12 months, mice were assessed for characteristics of metabolic syndrome that included weight, glucose and insulin tolerance." (PMID 32273396, 2020). "Allogenic FMT using METS-D decreases insulin sensitivity in metabolic syndrome recipients when compared with using post-RYGB-D." (PMID 31147381, 2020). "The GSE improved fat pad weights and morphology as well as clinical measures of insulin sensitivity and dyslipidemia." (PMID 33233708, 2020). "Treatment with a CB1 inverse agonist SR141716 (rimonabant) improves glycaemic control, insulin resistance, and dyslipidemia." (PMID 31653030, 2019).
metabolic syndrome (continued). "Attenuated post-prandial glucose and improvements in insulin sensitivity in adults with metabolic syndrome have been observed in human trials following RS intake." (PMID 31484331, 2019). "The components of the metabolic syndrome that tend to improve most (together with insulin sensitivity) are fasting triglycerides, indices of glycemia and systolic blood pressure." (PMID 31474943, 2019). "The 20 insulin resistant subjects consumed the RS supplement for 12 weeks that improves insulin sensitivity in metabolic syndrome." (PMID 31636690, 2019). "Resistant starch (RS) has been shown to improve postprandial glycemia and insulin sensitivity in adults with metabolic syndrome." (PMID 31484331, 2019). "It is well known that exercise training exerts beneficial metabolic adaptations including improvement in insulin sensitivity and mitochondrial biogenesis in skeletal muscle, improvement of dyslipidemia, and reduction of body fat." (PMID 30705516, 2019). "Clinically, aliskiren is reported to lower blood pressure and improve whole-body insulin sensitivity in male and female hypertensive patients with metabolic syndrome." (PMID 31262355, 2019). "Recent research connects acetate production by gut microbiota to metabolic syndrome via interaction with the host parasympathetic nervous system to promote insulin secretion." (PMID 31098399, 2019). "Circulating chemerin levels have also been reported to be higher in obese subjects compared to those with a normal BMI and significantly correlated with metabolic syndrome parameters, such as BMI, triglycerides, and fasting serum insulin." (PMID 31382403, 2019). "Physical activity can improve insulin sensitivity, alleviate plasma dyslipidemia, normalize elevated blood pressure, decrease blood viscosity, promote endothelial nitric oxide production, and improve leptin sensitivity to protect the heart and vessels." (PMID 31093312, 2019). "PCLSs, prepared from liver tissue obtained from male Wistar rats, were cultured in supraphysiological concentrations of glucose, fructose, insulin, and palmitic acid to mimic metabolic syndrome." (PMID 30818824, 2019). "In contrast to eWAT, CLE and LU suppressed the expression of lipogenic genes in the liver, ameliorating hepatic steatosis and, consequently, enhancing hepatic insulin sensitivity and dyslipidemia." (PMID 31208033, 2019). "The prevalence of metabolic syndrome was strongly increased (44% vs. 10%), whereas insulin sensitivity was decreased in men with Klinefelter syndrome (KS) compared with healthy controls." (PMID 31687020, 2019). "Animal studies reported that male and female ESR1 gene knockout mice developed features of the metabolic syndrome (MetS) including obesity caused by impaired fatty acid oxidation, glucose intolerance, and impaired insulin sensitivity, thus revealed the critical role of ESR1 in metabolic homeostasis." (PMID 31293826, 2019). "Impaired insulin signalling leads to metabolic syndrome, but the regulation of this process is not well understood." (PMID 30679431, 2019). "At that time, his medication was 160 mg/day of fenofibrate for the treatment of dyslipidemia and insulin therapy (18 units of glargine) for T2DM." (PMID 31470836, 2019). "We have recently introduced a novel marker with high sensitivity and specificity values, InsuTAG, that considers both insulin and triglycerides for identifying individuals with IR and metabolic syndrome." (PMID 30684965, 2019). "In particular, we investigated the lipid profile, insulin sensitivity and other indicators of metabolic syndrome." (PMID 31689911, 2019). "Previous study showed that acute pistachio intake alone had minimal effects on blood glucose and insulin levels in subjects of metabolic syndromes." (PMID 31921879, 2019). "AUC was calculated by ROC analysis for all surrogate insulin measures in diagnosis of metabolic syndrome." (PMID 31223343, 2019).
metabolic syndrome (continued). "In our study, the HFD provoked an impaired response to both glucose and insulin, confirming the two typical resistance forms of metabolic syndrome." (PMID 31374931, 2019). "Rat studies have shown that removal of visceral adipose tissue increases insulin sensitivity while delaying T2D, and prevents metabolic syndrome and NAFLD." (PMID 31231311, 2019). "Briefly, there is a significant difference between the two groups (i.e., MetS and Healthy) in terms of the metabolic syndrome, visceral fat, maximal oxygen uptake, and in the homeostatic model assessment 2 for insulin resistance." (PMID 31208054, 2019). "Moderate intensity exercise resulted in persistent beneficial effects for blood pressure, fasting insulin, and waist circumference — all strong measures of metabolic syndrome." (PMID 31040797, 2019). "Our results are consistent with previous findings in which patients who underwent KT and had PAS exhibited a higher prevalence of metabolic syndrome and its components, higher serum insulin levels, and HOMA-IR." (PMID 31450550, 2019). "Other studies have found that PCK1 gene silencing can improve glycemic control, insulin sensitivity, and aberrant dyslipidemia in Leprdb/J mice." (PMID 31805072, 2019). "This synthesis pathway with the use of sterol regulatory element-binding transcription factor 1 (SREBP-1c) is stimulated by high levels of insulin and cholesterol, which accompany the metabolic syndrome." (PMID 30959940, 2019). "To assess effect of excessive backfat thickness of sows during late pregnancy on metabolic syndrome in perinatal sows, we examined the biomarkers related to insulin sensitivity and systemic inflammation." (PMID 31881697, 2019). "The associations between weight gain and outcomes were confirmed after adjusting for baseline FBG, dyslipidemia, hypertension, waist circumference, insulin use and estimated glomerular filtration rate (model 3)." (PMID 30890169, 2019). "A study in rats with fructose-induced metabolic syndrome showed that dietary sardine protein lowered inflammation and oxidative stress, which are well-established factors negatively influencing insulin sensitivity." (PMID 31382619, 2019). "The uncontrolled high-fasting insulin level is considered as the earliest sign of the onset of metabolic syndrome." (PMID 31836013, 2019). "Associated with the metabolic syndrome, NAFLD is mostly driven by insulin-resistant white adipose tissue lipolysis that results in an increased hepatic fatty acid influx and the ectopic accumulation of fat in the liver." (PMID 31426291, 2019). "The CETP-mediated pathway has found to play a crucial role in dyslipidemia among the obese and insulin resistant individuals." (PMID 31259100, 2019). "Since skeletal muscle is an insulin-response target tissue, patients with sarcopenia develop progressive metabolic syndrome." (PMID 31882910, 2019). "In fact, tesaglitazar effectively improves insulin sensitivity and lowers circulating lipid levels better than PPARγ-selective agonists in subjects with metabolic syndrome." (PMID 31725756, 2019). "Fasting blood glucose, HDL, triglyceride, and fasting insulin levels were significantly higher in the metabolic syndrome group compared to the control group." (PMID 30862094, 2019). "CB2 inverse agonists have also been proposed to modulate the metabolic syndrome, in particular triglycerides, insulin, adipose tissue, and arterial pressure." (PMID 31653030, 2019). "With an increasing degree of metabolic syndrome components (i.e., metabolic syndrome score), there is an increase in fasting glucose, insulin levels, and HOMA IR." (PMID 31331009, 2019). "Metabolic syndrome consists of obesity, elevated blood pressure (i.e., hypertension (HPT)), impaired insulin sensitivity, and dyslipidemia." (PMID 29735938, 2018).